CRP (C-reactive protein)
Diseases named in the same sentence as CRP in open-access papers (continued):
Sharing a sentence is not in itself a finding about the gene and the disease.
uveitis (continued). "When statistical comparisons were made between the findings of BD and albumin, CRP and CAR levels, the presence of papulopustular lesion, the presence of uveitis and uveitis activity, and the elevation of CRP and CAR levels were statistically significantly higher (p < 0.05)." (PMID 39050391, 2024). "Among patients younger than 18 years with uveitis, those with CRP levels less than 1 mg/dL had a higher risk of cataract development (HR, 6.06; 95% CI, 2.35-15.62) compared with those without uveitis." (PMID 38949811, 2024). "Also, higher mean levels of CRP in patients with uveitis and IBD suggest a cumulative exposure to inflammation, although no data on diagnostic delay were reported." (PMID 37184889, 2024). "To date, the co-administration of probiotics and prebiotics (the so-called symbiotics) proved successful in reducing the clinical symptoms and the inflammatory parameters (i.e., C-reactive protein (CRP), hs-CRP, and erythrocyte estimated sedimentation rate) in an uveitis patient." (PMID 37686143, 2023). "Moreover, CRP concentrations can vary from relatively normal to notably elevated values in uveitis cases." (PMID 37873776, 2023). "However, the CRP level tended to be higher in patients with uveitis (MD 1.48; 95% CI − 0.17 to 3.14 mg/L)." (PMID 37679498, 2023). "Her renal function was stabilized with cyclophosphamide pulse therapy followed by corticosteroids and multiple immunosuppressants, while her meningitis, uveitis, and CRP levels significantly improved with IL-1-receptor antagonist anakinra, other than TNF-α monoclonal antibody therapy." (PMID 34249981, 2021). "Of the patients with HLA B27-associated uveitis without systemic involvement, 2/8, 25% exhibited CRP ≥ 10 mg/L and 1/8, 13% had both ESR ≥ 20 mm/h and CRP ≥ 10 mg/L." (PMID 30411142, 2019). "Herein, we investigate the values of ESR and CRP during the first episode of active uveitis, determined within a short period after the onset in adult patients and relate the results to specific etiologic categories and clinical characteristics of uveitis." (PMID 30411142, 2019). "Compared to non-SpA patients, SpA patients were more frequently male urban dwellers, they were significantly younger, they had a higher prevalence of HLA-B27 and recurrent uveitis, and they had higher median of C-reactive protein and lower median of white blood counts." (PMID 30206560, 2018). "The association of recurrent uveitis with male gender and young age was previously reported in literature, but to our knowledge, the association with higher CRP and normal WBC was not previously reported." (PMID 30206560, 2018). "Furthermore, incorporating laboratory results such as leukocyte counts, C-reactive protein (CRP) levels, and antiretinal antibodies could provide deeper insights into the relationship between uveitis and DS." (PMID 38792893, 2024). "The remaining five patients had uveitis limited to the eye, but had a concurrent systemic disorder, which explained their highly elevated ESR and/or CRP but was not related to the cause of uveitis (such as multiple myeloma in a patient with infectious uveitis)." (PMID 30411142, 2019). "Their results indicated a significant positive correlation of NAR with clinical and laboratory parameters of BD activity (active uveitis, arthralgia, and oral ulceration), as well as with parameters CRP, ESR, and CRP/albumin ratio (CAR)." (PMID 41230322, 2025). "B27+ and B27− patients differed with regard to age, sex, BASDAI, C-reactive protein (CRP), body mass index, enthesitis, uveitis, and classification status." (PMID 36574181, 2023). "There are known predictors of uveitis in JIA, such as female gender, younger-onset age, ANA-positivity, oligoarticular course, and high CRP, but data about the features of the arthritis course in patients with concomitant uveitis are scarce." (PMID 35783325, 2022). "Previous investigations have showed the increased expression of circulating CRP, IL-6 and TNF-α in the uveitis." (PMID 36275682, 2022).
uveitis (continued). "We identified 20 JIA patients with clinical (presence of arthritis or uveitis) or laboratory (ESR ≥15 mm/h; CRP> 0.5 mg/dL) disease activity." (PMID 36096831, 2022). "This assesses 8 domains including active joint count, enthesitis count, patient pain assessment, inflammation (either CRP or ESR), morning stiffness, clinical evaluation of sacroiliitis, uveitis, and back mobility measured by the modified Schober's test." (PMID 34136509, 2021). "This was done by analyzing a large number of laboratory parameters for pediatric uveitis, including ANA, RF, ASO (anti-streptolysin "O"), CRP (C-reactive protein), ANCA (anti-neutrophil cytoplasmic antibodies), and ESR (erythrocyte sedimentation rate)." (PMID 24020968, 2013). "First, our study found that the baseline CRP and leukocyte levels were higher among patients younger than 18 years with uveitis than among those without uveitis." (PMID 38949811, 2024). "Our findings revealed higher baseline mean CRP leukocyte levels among patients with uveitis than among those without uveitis." (PMID 38949811, 2024). "The CRP level was non-significantly higher in patients with uveitis than in those without uveitis (MD 1.48; 95% CI − 0.17 to 3.14 mg/L, p = 0.08)." (PMID 37679498, 2023). "The pooled mean CRP levels were 15.78 (95% CI 8.38 to 23.18) mg/L and 14.53 (95% CI 8.69 to 20.38) mg/L in patients with and without uveitis, respectively." (PMID 37679498, 2023). "A complete work-up for uveitis, including antinuclear antibodies (ANA), anti-neutrophil cytoplasmic antibodies (ANCA), rheumatoid factor (RF), angiotensin-converting-enzyme (ACE), C-reactive protein (CPR), erythrocyte sedimentation rate (ESR), lysozyme and calcium serum levels were normal." (PMID 37834885, 2023). "In conclusion, the vitreous IL-6 level was significantly higher in male patients, and non-infectious uveitis cases showed a significant correlation between CRP and vitreous IL-6 levels." (PMID 36902507, 2023). "In addition, previous researchers have found the increased expression of circulating CRP, IL-6, and TNF-α in the uveitis." (PMID 36275682, 2022). "After 6 months, the patient was asymptomatic, without lumbar pain; she also showed normalization of the erythrocyte sedimentation rate and the C-reactive protein and vitamin D levels, good control of lumbar pain, and no new uveitis episodes." (PMID 34900358, 2021). "Complete bloodwork performed by a uveitis specialist demonstrated high ESR and CRP levels." (PMID 34394876, 2021). "In this retrospective, cross-sectional study, the majority of patients with a first active episode of uveitis of unknown origin presented with normal ESR and CRP values." (PMID 30411142, 2019). "In conclusion, our study reflects that presence of uveitis alone is not sufficient to cause elevation of ESR and/or CRP as a majority of patients with a first uveitis episode had ESR and CRP values within the normal limits." (PMID 30411142, 2019). "The majority of patients with first attack of uveitis had ESR and CRP within the normal limits." (PMID 30411142, 2019). "To minimize potential bias, we restricted the cohort to patients without a prior diagnosis of uveitis and adjusted for disease severity proxies, including baseline CRP, ESR, and prior exposure to conventional synthetic DMARDs within the year before treatment initiation." (PMID 41208989, 2025). "In contrast, significantly more men vs women with r-axSpA had elevated CRP levels, regardless of TNFi use (TNFi users, 66.7% vs 48.6% [P = 0.0056]; no TNFi use, 55.5% vs 33.3% [P < 0.001]), and occurrences of uveitis (15.1% vs 4.1%; P = 0.0122) in TNFi users but not among non-users." (PMID 40833778, 2025). "Also, the present study showed that the mean of WBC, platelet, and CRP in the group with uveitis involvement was higher than that of the group without involvement." (PMID 38693550, 2024).
uveitis (continued). "Suspected BD patients exhibited significantly higher levels of inflammatory markers (CRP, ESR) and characteristic clinical features such as oral/genital ulcers and uveitis compared to non-BD patients." (PMID 41900928, 2026). "Patients with uveitis had significantly higher rates of Coronary artery dilatation and IVIG resistance, as well as higher mean levels of WBC, platelet, and CRP compared to those without uveitis." (PMID 38693550, 2024). "A complete workup for uveitis was negative (blood cell count, VDRL, TPHA, quantiferon TB gold, HIV, ESR, CRP, blood sugar concentration, creatinine, liver enzymes, urine analysis and chest X-ray) and a diagnosis of VKH was made." (PMID 37834885, 2023). "In the standardized group, patients had a minimal work-up regardless of the type of uveitis (including evaluation of the CBC, ESR, C-reactive protein, tuberculin skin test, syphilis serology and chest X-ray)." (PMID 32059021, 2020). "In addition, in their study, age, CRP, ESR, and neutrophil count were higher in patients with uveitis than those without uveitis." (PMID 38693550, 2024).
lower respiratory tract infections (81 papers, 2006 to 2026). "The patients experienced repeated skin abscesses caused by S. aureus, upper and lower respiratory tract infections, though intriguingly their levels of C-reactive protein (CRP) were only slightly elevated during acute infection." (PMID 40040707, 2025). "Most COPD exacerbations are due to lower respiratory tract infections that are associated with an acute phase response with a rise in systemic inflammatory markers such as C reactive protein (CRP)." (PMID 30257486, 2018). "Higher maternal plasma levels of IL-6 and CRP have also been associated with alterations in fetal growth and brain development, wheezing and lower respiratory tract infections, the incidence of which is increased in offspring of obese mothers." (PMID 30131724, 2018). "The views about the diagnostic value of CRP in infections of the lower respiratory tract are, however, controversial." (PMID 25655784, 2015). "Until now, the diagnostic value of CRP for primary care was mostly evaluated for acute inflammatory diseases like lower respiratory tract infection (LRTI) and acute maxillary sinusitis." (PMID 16670014, 2006). "Seppa and colleagues reported that CRP level ≥100 mg/L was a marker independently associated with higher risk of death in patients with lower respiratory tract infections." (PMID 16899118, 2006). "Indeed, increased maternal CRP during pregnancy is linked to a higher risk of eczema, and CR in cord blood to a higher possibility of wheezing and lower respiratory tract infections in the first 4 years." (PMID 37873776, 2023). "Point-of-care CRP testing has proven effective in reducing antibiotic consumption for lower respiratory tract infections in nursing homes." (PMID 39163362, 2024). "Interpretation of C-reactive protein concentrations in adults with lower respiratory tract infection." (PMID 39100952, 2024). "The introduction of antimicrobial therapy during lower respiratory tract infections can be guided by the implementation of biomarkers (PCT or CRP), and the excessive use of prescribing antibiotics in health care can be decreased." (PMID 37627950, 2023). "The management algorithm used a CRP cut-off of 50 mg/l, since a randomised controlled trial in Vietnam demonstrated that it is safe to withhold antibiotics in children with acute lower respiratory tract infections if the CRP is < 50 mg/l." (PMID 37488633, 2023). "The CRP test is the most widely used serum biomarker in the differential diagnosis (viral or bacterial etiology) of lower respiratory tract infections." (PMID 35453219, 2022). "PCT and CRP have proven helpful in lower respiratory tract infections and help to differentiate between pure viral or secondary infection." (PMID 36301096, 2022). "Point-of-care (POC) testing for CRP has been shown in randomised trials to reduce the amount of antibiotics prescribed for lower respiratory tract infections and cases of COPD exacerbation in community settings." (PMID 35892398, 2022). "Guidance on the CRP thresholds above which antibiotics should be considered in patients with suspected lower respiratory tract infection followed NICE guidance at that time." (PMID 35232491, 2022). "CRP POCT for suspected lower respiratory tract infection safely reduced antibiotic prescribing compared with usual care in nursing home residents." (PMID 34548288, 2021). "The measurement of C-Reactive Protein (CRP) at the point of care (PoC) in patients presenting symptoms of lower respiratory tract infections (LRTI) can support appropriate antibiotic prescribing in primary care." (PMID 31527896, 2019). "Utilisation of point-of-care C-reactive protein testing for lower respiratory tract infection has been limited in UK primary care, with costs and funding suggested as important barriers." (PMID 30366918, 2018). "Following clinical guideline, CRP testing in patients with lower respiratory tract infections (LRTIs) cost £4390 per QALY gained and £9.31 per antibiotic prescription avoided." (PMID 30544560, 2018).
lower respiratory tract infections (continued). "Overprescription of antibiotics for lower respiratory tract infections (LRTIs) in children is common, partly due to diagnostic uncertainty, in which case the addition of point-of-care (POC) C-reactive protein (CRP) testing can be of aid." (PMID 30564733, 2018). "In patients with lower respiratory tract infections, copeptin predicted mortality more accurately than C-reactive protein (CRP) and leucocyte count." (PMID 29100503, 2017). "The CRP distribution was similar to what has been observed in European primary care studies on lower respiratory tract infections." (PMID 26769226, 2016). "Relationship between CRP and infection of the lower respiratory tract was indicated by different studies in literature." (PMID 23497669, 2013). "There is little other published primary care data available evaluating CRP in the treatment of lower respiratory tract infections in routine clinical practice." (PMID 21880122, 2011). "A recent study demonstrated that CRP testing resulted in decreased antibiotic prescribing for lower respiratory tract infection in primary care." (PMID 21880122, 2011). "Much previous work on the use of CRP levels has been in reference to its use in lower respiratory tract infections." (PMID 21880122, 2011). "There are limited studies to date involving point-of-care testing in care home settings; one Dutch study has shown that a point-of-care C-reactive protein could safely reduce antibiotic prescribing for lower respiratory tract infection." (PMID 40335096, 2025). "Another publication dealt with lower respiratory tract infections, by testing C-reactive protein." (PMID 35054270, 2022). "The use of CRP to support antibiotic prescribing decisions for suspected lower respiratory tract infection was supported by the National Institute for Health and Care Excellence Clinical Guideline CG191 (withdrawn after the start of the COVID-19 pandemic) and has been discussed elsewhere." (PMID 35232491, 2022). "C reactive protein point-of-care testing (CRP POCT) for suspected lower respiratory tract infections might contribute to prompt and appropriate decisions of whether or not to prescribe antibiotics, or to suggest additional investigations." (PMID 34548288, 2021). "In this cluster randomised controlled trial we showed that CRP POCT for nursing home residents with suspected lower respiratory tract infection resulted in a large, clinically relevant and safe reduction in antibiotic prescribing at initial consultation in comparison with usual care." (PMID 34548288, 2021). "Procalcitonin (PCT) and CRP have proven useful in other lower respiratory tract infections and might help to differentiate between pure viral or secondary infection." (PMID 34021897, 2021). "In a cluster randomised controlled trial we evaluated whether CRP POCT results in a safe reduction in antibiotic prescribing for nursing home residents with suspected lower respiratory tract infection compared with usual care." (PMID 34548288, 2021). "The mean CRP levels in patients with lower respiratory tract infections were 155.2 ± 119.1 mg/dl." (PMID 32821576, 2020). "Recent data suggested that CRP could be of more help in assisting in the diagnosis of lower respiratory tract infections (LRTI)." (PMID 26472401, 2015). "Consequently, the British Medical Journal highlights that the C-reactive protein assay does not have adequate sensitivity and specificity to differentiate between infiltrates on chest X-rays and the bacterial causes of lower respiratory tract infections." (PMID 39635594, 2024). "An interesting review article concluded that CRP testing is neither sufficiently sensitive to exclude nor sufficiently specific to rule in an infiltrate on chest radiograph and the bacterial cause of lower respiratory tract infection." (PMID 37873776, 2023).